AK2 (adenylate kinase 2)
Description:
Catalyzes the reversible transfer of the terminal phosphate group between ATP and AMP. Plays an important role in cellular energy homeostasis and in adenine nucleotide metabolism. Adenylate kinase activity is critical for regulation of the phosphate utilization and the AMP de novo biosynthesis pathways. Plays a key role in hematopoiesis.
Synonyms: ADK2
Tractability: Small molecule: a structure with a bound ligand is known; a high-quality ligand is known. PROTAC: ubiquitination databases record sites on it; its protein half-life has been measured; a small molecule that binds it is known.
Target class: Enzyme
Gene: Protein-coding gene on chromosome 1 (33,007,986 to 33,080,996, reverse strand). Ensembl gene ENSG00000004455.
Subcellular location: Mitochondrion intermembrane space
Subcellular location (Human Protein Atlas): Mitochondria
Pathways (Reactome):
Metabolism: Interconversion of nucleotide di- and triphosphates
Gene Ontology:
Molecular function: AMP kinase activity; protein binding; ATP binding; nucleobase-containing compound kinase activity; phosphotransferase activity, phosphate group as acceptor
Biological process: ADP biosynthetic process; nucleobase-containing small molecule interconversion; AMP metabolic process; ATP metabolic process; nucleobase-containing small molecule metabolic process
Cellular component: extracellular exosome; mitochondrion; mitochondrial intermembrane space; sperm flagellum; sperm mitochondrial sheath
Genetic constraint (gnomAD): Loss-of-function variants: 15 observed, 24.21 expected, observed/expected ratio (o/e) 0.62, 90% interval 0.41 to 0.95. The upper end of that interval is the gene's LOEUF score, 0.95, which puts it in group 4 of 6, group 1 being the genes least tolerant of losing a copy. Missense variants: 257 observed, 293.14 expected, observed/expected ratio (o/e) 0.88, 90% interval 0.79 to 0.97. Synonymous variants: 102 observed, 105.25 expected, observed/expected ratio (o/e) 0.97, 90% interval 0.82 to 1.14.
Gene-disease validity (ClinGen):
ClinGen rates the evidence that AK2 causes each of these diseases.
reticular dysgenesis (autosomal recessive): Definitive. Reticular dysgenesis is the most severe form of severe combined immunodeficiency (SCID) and is characterized by bilateral sensorineural deafness and a lack of innate and adaptive immune functions leading to fatal septicemia within days after birth if not treated.
Homologues: Orthologues: macaque AK2 (97% identical), chimpanzee AK2 (97% identical), dog AK2 (95% identical), mouse Ak2 (95% identical), guinea pig AK2 (94% identical), rabbit AK2 (92% identical), rat Ak2 (90% identical), zebrafish ak2 (79% identical), tropical clawed frog ak2 (78% identical), Drosophila melanogaster Ak2 (64% identical), Caenorhabditis elegans let-754 (62% identical). Paralogues in human: AK3 (40% identical), AK4 (38% identical), AK4P3 (38% identical), AK1 (28% identical), CMPK1 (26% identical), AK5 (25% identical), AK7 (23% identical), AK8 (22% identical), AK9 (20% identical).
Diseases named in the same sentence as AK2 in open-access papers:
AK2 is named in the same sentence as 67 diseases in open-access papers, as found by Europe PMC text mining. Sharing a sentence is not in itself a finding about the gene and the disease. The quoted sentences say what the papers report.
hepatocellular carcinoma (12 papers, 2020 to 2025). A malignant tumor that arises from hepatocytes. "Adenylate kinase 2 K28la reduces its activity, stimulating hepatocellular carcinoma proliferation and metastasis." (PMID 40994548, 2025). "Adenylate kinase 2 K28la substantially decreases the enzymatic activity and is correlated with hepatocellular carcinoma progression." (PMID 40994548, 2025). "For instance, lactylation of adenylate kinase 2 at the K28 site has been found to inhibit its function, thereby facilitating proliferation and metastasis in hepatitis B virus-related hepatocellular carcinoma cells." (PMID 40082399, 2025). "Specifically, lactylation at K28 of adenylate kinase 2 inhibited its activity, thereby facilitating the proliferation and metastasis of hepatocellular carcinoma cells." (PMID 40784455, 2025). "For example, the lactylation of adenylate kinase 2 has been shown to enhance the proliferation and metastasis of hepatocellular carcinoma (HCC)." (PMID 38291438, 2024). "There are some contradictory studies where it was found that in lung cancer and hepatoma, AK was downregulated compared with that in normal tissue, whereas a recent study has shown that high expression of AK2 correlates with a worse prognosis for lung cancer patients." (PMID 32509571, 2020). "In addition, in hepatoma cells, it was found that up to 50% of ATP is provided by intramembrane space located AK2 through VDAC binding to HK." (PMID 32509571, 2020). "Lysine lactylation (Kla) at the K28 site facilitated the proliferation and metastasis of hepatocellular carcinoma (HCC) cells by inhibiting the function of adenylate kinase 2 (AK2)." (PMID 39502530, 2024). "This includes various proteins such as HMGB1, METTL3, PKM2, and AK2, and spans a wide range of diseases including sepsis, liver IRI, colon cancer, skin wounds, and hepatocellular carcinoma." (PMID 40082399, 2025). "In hepatocellular carcinoma (HCC), the residue lysin 28 lactylation impedes adenylate kinase 2 (AK2) activity to induce the proliferation and metastasis of HCC cells." (PMID 37945340, 2023). "In addition, lactylation at the K28 site of the metabolic enzyme adenylate kinase 2 (AK2) inhibits its enzymatic activity, thereby enhancing the growth and spread of hepatocellular carcinoma." (PMID 40589733, 2025). "Lactylation modification inhibits Adenylate Kinase 2 (AK2) function and promotes the proliferation and metastasis of hepatoma cells, which may be related to drug resistance." (PMID 41179284, 2025).
reticular dysgenesis (11 papers, 2010 to 2026). "Reticular dysgenesis (RD) is a rare genetic disorder caused by mutations in the adenylate kinase 2 (AK2) gene." (PMID 40654267, 2025). "Mechanistically, this is studied in patients suffering from reticular dysgenesis (RD), which is caused by an AK2 deficiency." (PMID 38450755, 2024). "It is a unique example of an immune deficiency that is linked to dysfunctional mitochondrial energy metabolism and caused by adenylate kinase 2 (AK2) deficiency." (PMID 31673062, 2019). "Mutations in the gene AK2 are responsible for reticular dysgenesis (RD), a rare and severe form of primary immunodeficiency in children." (PMID 31727854, 2019). "All HSCTs resulted in successful engraftment and immune reconstitution, except for one child with reticular dysgenesis associated with an AK2 gene variant, who underwent unrelated donor HSCT at 3 months 2 weeks but died on day 12 post-transplant due to infectious complications." (PMID 41459527, 2025). "Reticular dysgenesis (RD) is a rare congenital disorder caused by mutations in the gene encoding adenylate kinase 2 (AK2)." (PMID 38921186, 2024). "Recently a mutation in the gene coding for the mitochondrial energy metabolism enzyme adenylate kinase 2 (AK2) has been identified in six individuals with reticular dysgenesis from five independent families." (PMID 20465788, 2010). "In patients with AK2 deficiency (Reticular Dysgenesis), transplantation without conditioning is associated with a high risk of primary graft failure especially in haploidentical transplantation with in vitro T-cell depletion of the graft." (PMID 34226669, 2021). "Reticular dysgenesis (RD) (MIM267500; aleukocytosis) is an autosomal recessive form of severe combined immunodeficiency (SCID) resulting from defects in the adenylate kinase 2, AK2, gene located on chromosome 1p35.1." (PMID 31673062, 2019). "In addition, two other studies reported that AK2 is a responsible gene for reticular dysgenesis (RD), a human disease that is characterized by severe combined immunodeficiency and deafness." (PMID 24587121, 2014).
breast carcinoma (10 papers, 2013 to 2023). "Loss of AK2 expression is associated with rapid cell proliferation and often found in breast cancers, providing a molecular basis for the role of AK2/DUSP26 complex as a potent regulator of tumour growth." (PMID 24548998, 2014). "The over-expressed of AK2 and other genes was reported to be a factor in the growth of breast cancer that was invasive." (PMID 37752559, 2023). "In breast cancer, AK2 downregulation results in reduced interaction of AK2-DUSP26 complex with FADD and, subsequently, increased phosphorylated FADD levels in the nuclei of tumor cells, correlating with increased proliferation." (PMID 31569512, 2019). "Western blotting of 14 human breast cancers showed that AK2 expression was abolished or low in cancer tissues compared with non-cancerous tissues." (PMID 24548998, 2014). "Recently, the role of AK2 in tumorigenesis was in part elucidated in some cancer types including lung adenocarcinoma and breast cancer, but the underlying mechanism is not clear." (PMID 35585049, 2022). "Moreover, dataset analysis showed that AK2 was a prognostic marker for aggressive breast cancer with positive lymph node." (PMID 35712500, 2022). "Interestingly, high AK2 levels of tumors were associated with poor outcome of distant metastasis-free survival in breast cancer patients with positive lymph node compared to those tumors which have low level of AK2." (PMID 35712500, 2022). "Finally, we interrogated a large compendium of 2999 breast cancers to assess whether there was selective pressure to overexpress AK2 in MYC-high tumours." (PMID 35945217, 2022). "Thus, downregulation of AK2 expression seen here in the human breast cancers may regulate cell proliferation that is contributed by the phosphorylation of their substrate, FADD." (PMID 24548998, 2014). "Analysis of the four AK genes (AK1, AK2, AK4, and AK6) mRNA expression in breast cancer cells revealed several alterations in the composition of the AK network." (PMID 35712500, 2022). "Lamb and colleagues have shown on the breast cancer model that mitochondrial mass is a new biomarker of CSC, which have increased AK2 expression level." (PMID 32509571, 2020). "Despite the decreased overall phosphoryl flux, overexpression of HK2, AK2, and AK6 isoforms within cell compartments could promote aggressive breast cancer growth." (PMID 35712500, 2022). "Moreover, all of the five cancers (100%) showing high level of p-FADD signal ablated the expression of both AK2 and DUSP26, underscoring a strong cross-talk for an inverse correlation between AK2/DUSP26 expression and p-FADD in the human breast cancers." (PMID 24548998, 2014). "Dysregulation of this AK2/DUSP26/FADD signalling pathway does not have to be limited to breast cancer." (PMID 24548998, 2014). "In addition, AK2 expression was also downregulated in other HS-578T, MDA-MB-453, BT-474 and SK-BR-3 breast cancer cells among total eight breast cancer cell lines." (PMID 24548998, 2014). "Although AK2 expression was detected in most cancer cells, including SK-Hep1 and HepG2 hapatocellular carcinoma cells, its expression was drastically downregulated in MCF-7 breast cancer cells and C33A cervical cancer cells." (PMID 24548998, 2014).
lung adenocarcinoma (8 papers, 2019 to 2023). A carcinoma that arises from the lung and is characterized by the presence of malignant glandular epithelial cells. "AK2 is overexpressed in lung adenocarcinoma, and the positive expression of AK2 is associated with tumor progression and reduced survival in patients." (PMID 36982634, 2023). "Recent studies provided evidence that AK2 is overexpressed in lung adenocarcinoma, and is associated with tumor progression." (PMID 35574395, 2022). "The knockdown of AK2 inhibits the proliferation, migration, and invasion of human lung adenocarcinoma cells, induces apoptosis and autophagy." (PMID 36982634, 2023). "In conclusion, we provide insight into the biological function of AK2 in human lung adenocarcinoma and demonstrate that AK2 overexpression activates the TGF-β/Smad3/Smad2/Smad4 signaling pathway, leading to enhanced invasion via EMT." (PMID 34630090, 2021). "Knockdown or knockout of AK2 inhibited, while overexpression of AK2 promoted, human lung adenocarcinoma cell migration and invasion ability." (PMID 34630090, 2021). "Bioinformatic analysis showed that AK2 expression levels significantly increased in lung adenocarcinoma (LUAD) and lung squamous cell carcinoma (LUSC) than that in normal tissues, and the p-values were all less than 0.0001." (PMID 34630090, 2021). "Positive expression of AK2 is related to lung adenocarcinoma progression and poor survival of patients." (PMID 34630090, 2021). "The knockdown of AK2 suppressed proliferation, migration, and invasion, as well as induced apoptosis and autophagy in human lung adenocarcinoma cells." (PMID 32509571, 2020). "Knockdown of overexpressed AK2 in human lung adenocarcinoma cells suppressed proliferation, migration, and invasion as well as induced apoptosis and autophagy." (PMID 32509571, 2020). "To further confirm AK2 expression in lung adenocarcinoma, we downloaded and analysed the existing clinical data from The Cancer Genome Atlas (TCGA) database including 548 pairs of cancer and paracancerous tissues from LAD." (PMID 31780678, 2019). "The immunohistochemical results in the 345 cases of lung adenocarcinoma revealed that expression of AK2 was significantly upregulated in tumors with the advanced stage, larger tumor size, lymph node metastasis, and acinar predominant subtype." (PMID 31780678, 2019). "In this study, we firstly conducted immunohistochemical experiments on lung adenocarcinoma tumor tissues of clinical patients, and found that AK2 intensity in the left frontal lobe metastatic carcinoma (from lung adenocarcinoma) tissue were significantly increased." (PMID 34630090, 2021). "In this study, we showed that AK2 regulated tumor cell metastasis in lung adenocarcinoma." (PMID 34630090, 2021). "Knockdown of AK2 suppressed proliferation, migration, and invasion as well as induction of apoptosis and autophagy in human lung adenocarcinoma cells, and even greater tumor suppression was observed when AK2 silencing was combined with hydroxychloroquine, an effective autophagy inhibitor." (PMID 33499187, 2021). "In their research, they found that knockdown of AK2 could markedly suppress the proliferation and facilitate the apoptosis in lung adenocarcinoma cells." (PMID 34630090, 2021). "Furthermore, a recent study showed that AK2 has prognostic and therapeutic potential in lung adenocarcinoma." (PMID 32509571, 2020). "Knockdown of AK2 could suppress proliferation, migration, and invasion as well as induce apoptosis and autophagy in human lung adenocarcinoma cells." (PMID 31780678, 2019). "In this study, we provided the first evidence that AK2 is overexpressed in lung adenocarcinoma." (PMID 31780678, 2019). "Similarly, the knockdown or knockout of AK2 inhibits the migration and invasive potential of human lung adenocarcinoma cells, while its overexpression promotes cancer metastasis, providing a rationale for targeting AK2 as a therapeutic approach for lung cancer." (PMID 36982634, 2023).
lung adenocarcinoma (continued). "However, our study shows that AK2 is an aggressive oncogene in lung adenocarcinoma." (PMID 31780678, 2019). "To explore the role of AK2 in NSCLC progression, we first evaluated AK2 expression in pathological tissue microarray from lung adenocarcinoma patients." (PMID 34630090, 2021). "Besides, it was also shown that AK2 is methylated with the development of antituberculosis drug-induced liver injury (ATLI) and overexpressed in lung adenocarcinoma and in metastatic pancreatic endocrine neoplasms, which preferentially metastasized to liver." (PMID 35585049, 2022). "Next, we examined AK2 level in the adjacent non-tumor tissues, primary lesion, and left frontal lobe metastasis from patients with stage IV lung adenocarcinoma by immunohistochemistry analysis." (PMID 34630090, 2021). "Therefore, the combination of AK2 knockdown and HCQ might synergistically improve therapy outcome in lung adenocarcinoma patients." (PMID 31780678, 2019).
lung carcinoma (8 papers, 2014 to 2023). "For Lung cancer, the positive expression of AK2 is associated with poor prognosis of pulmonary adenocarcinoma patients." (PMID 35712500, 2022). "Furthermore, there was a statistically significant inverse association between AK2 expression levels and recurrence-free survival, and high expression of AK2 significantly promoted the progress of lung cancer." (PMID 34630090, 2021). "Recent studies demonstrated that AK2 is overexpressed in Lung cancer cells and T-cell acute lymphoblastic leukemia cells." (PMID 35712500, 2022). "The expression levels of AK2 in a series of lung cancer cells (H1299, A549, H446, and 95D cells) and HBE cell line (a normal control group) were analyzed by qPCR assay." (PMID 34630090, 2021). "In conclusion, we uncover a cancer metastasis-promoting role for AK2 and provide a rationale for targeting AK2 as a potential therapeutic approach for lung cancer." (PMID 34630090, 2021). "We found that AK2 was almost undetectable in normal lung tissues, while its expression level in lung cancer tissues gradually increased with the progresses of cancer." (PMID 34630090, 2021). "Given that knockout of AK2 significantly inhibited lung cancer cell migration and invasion, we next investigated the effects of AK2 knockout in vivo using the mice passive lung metastasis model." (PMID 34630090, 2021). "AK2 promoted human lung cancer cells invasion in vitro and in vivo, and overexpression of AK2 fostered this progression by inducing EMT." (PMID 34630090, 2021). "To gain insight into the role of EMT played in lung cancer metastasis induced by knocking out of AK2, we evaluated the metastatic potential by lung colony formation efficiency using nude mice model." (PMID 34630090, 2021). "In this study, we found that AK2 is closely related to the occurrence and development of non-small cell lung cancer, especially lung cancer cell metastasis." (PMID 34630090, 2021). "The abnormally increased secretion of IL-6 was related to the regulation of growth and metastasis of lung cancer cells, and the activation of the IL-6/AK2/STAT3 pathway enhanced initiation of tumor in lung cancer." (PMID 32595734, 2020). "We also observed significant downregulation of AK2 in other cancers, such as liver and lung cancers." (PMID 24548998, 2014). "Considering the important role of EMT in tumor migration and invasion, we speculated that AK2 might affect lung cancer cell migration ability through the TGF-β/EMT process." (PMID 34630090, 2021). "Next in vitro experiments found that knockout or knockdown of AK2 could reduce lung cancer cells migration speed." (PMID 34630090, 2021). "In response to the absence of AK2, E-cadherin protein level increased significantly, indicating that AK2 might regulate EMT in lung cancer cells." (PMID 34630090, 2021). "Collectively, our data showed that AK2 is highly expressed in lung cancer and promotes lung cancer cell migration and invasion, which may be caused by the involvement of AK2 in the EMT process regulated by TGF-β/Smad signaling pathway." (PMID 34630090, 2021). "A series of signal pathways potentially regulated by AK2 was clustered and the lung cancer-related signaling pathways showed a high score, among which we found that AK2 might be involved in the TGF-β signaling pathway in lung cancer." (PMID 34630090, 2021). "Although earlier work has demonstrated the biochemical differences of AK2 in lung cancer cases, the molecular events that regulate tumor growth and metastasis are still unknown." (PMID 34630090, 2021). "Moreover, AK2 induces EMT through the Snail/Smads/TGF-β signaling pathway in lung cancer cells, thereby affecting migration and invasion." (PMID 34630090, 2021). "Moreover, we found that the EMT process also participated in the regulation of lung cancer migration in AK2-KO cells." (PMID 34630090, 2021).